AR (androgen receptor)
Diseases named in the same sentence as AR in open-access papers (continued):
Sharing a sentence is not in itself a finding about the gene and the disease.
prostate carcinoma (continued). "A significant subset of prostate cancer (PC) patients with a castration-resistant form of the disease (CRPC) show primary resistance to androgen receptor (AR)-targeting drugs developed against CRPC." (PMID 29988112, 2018). "Signaling by the androgen-induced androgen receptor (AR) promotes cell growth of prostate cancer (PC) cells." (PMID 29707137, 2018). "For example, FOXO3a is a positive regulator of androgen receptor expression and prostate cancer cell proliferation." (PMID 30478420, 2018). "We utilised cell line models of castrate resistant prostate cancer through over expression of AR-V7 to test the impact of chemical LSD1 inhibition on AR activation." (PMID 29760584, 2018). "We recently reported that angiotensin II receptor blockers (ARBs) have chemopreventive and chemotherapeutic potential against prostate cancer via the reduction of androgen receptor (AR) expression." (PMID 29568400, 2018). "Prostate cancer is an androgen-dependent carcinoma that is mediated through androgen receptor (AR)-regulated genes." (PMID 29757237, 2018). "The observed loss of ARCC-4 functional activity at higher R1881 concentrations clearly shows that our previously observed suppression of prostate cancer cell growth by ARCC-4 is indeed mediated through AR signaling." (PMID 30271980, 2018). "The androgen receptor (AR) plays a pivotal role in prostate cancer growth and androgen is known to exert its effects, in part by stimulating mTORC2 activation." (PMID 29301334, 2018). "This is in part because prostate cancers adaptively switch to the androgen/AR-independent pathway for survival and growth, thereby conferring therapy resistance." (PMID 30478344, 2018). "We inferred that the higher relative expression of CDK5 Isoform1 in cancer cells can plays an important role in AR-involved prostate cancer progression." (PMID 30367578, 2018). "Androgen receptor (AR) stimulation and downstream signaling is critical for the initiation and progression of prostate cancer." (PMID 30314329, 2018). "Sorafenib has also been demonstrated to decrease the proliferation of prostate cancer cells by inhibiting the androgen receptor and the Akt signaling pathway, thereby resulting in cell death." (PMID 30386849, 2018). "During prostate cancer, it is the aberrant AR signaling that results in the uncontrolled proliferation and survival of prostate cancer cells, especially in advanced hormone refractory disease where AR becomes active in the absence of a ligand." (PMID 29339807, 2018). "As such, epigenetic dysregulation represents a driving mechanism in the reprograming of prostate cancer cells as they lose AR-imposed identity." (PMID 29888169, 2018). "The androgen receptor (AR) was expressed in both androgen-dependent and -independent prostate cancer lines." (PMID 30361641, 2018). "Here we show the AR can couple hormone induced gene transcription to alternative mRNA isoform expression in prostate cancer." (PMID 30271587, 2018). "Once bound to AR, androgens play pivotal roles in the sexual development, function, musculoskeletal growth of male and the progress of prostate cancer." (PMID 30210333, 2018). "Prostate cancer (CaP) growth and progression rely on the activation of the androgen receptor (AR) by the testicular androgen, testosterone (T), or its more potent metabolite, dihydrotestosterone (DHT)." (PMID 29541409, 2018). "Prostate cancer initiation and progression are uniquely dependent on the androgen receptor (AR), a hormone-inducible DNA-binding transcription factor that plays a critical role in the development and function of the prostate." (PMID 29464071, 2018). "Theompounds isolated from Chinese herbs here discussed perform well in inhibiting the growth, proliferation, and metastasis of prostate cancer cells, and most of them act as selective androgen receptor modulators to exert anti-prostate cancer activity." (PMID 29495626, 2018).
prostate carcinoma (continued). "To further demonstrate the significance of TLX overexpression on the AR transactivation in androgen-stimulated prostate cancer cells, we examined the nuclear translocation of AR immunosignals in LNCaP-TLX infectants by immunofluorescence." (PMID 29555975, 2018). "We present a unique resource on transcriptional and epigenetic control in prostate cancer, revealing tight control of gene regulation differentially dictated by AR over three subtypes." (PMID 30464211, 2018). "Fibroblasts express androgen receptor (AR) in the normal prostate and during prostate cancer development." (PMID 29721186, 2018). "While most prostate cancer metastases were defined as AR-driven, some (about 20%) seemed to be non-AR-driven." (PMID 29670000, 2018). "Prx II-mediated distinct regulation of AR transactivation increases AR-expressing prostate cancer cell proliferation, cell growth and the progression of AR-expressing prostate cancers to castration-resistant prostate cancer (CRPC)." (PMID 30177619, 2018). "Androgen receptor (AR) plays a central role in many aspects of normal prostate development as well as prostate cancer progression." (PMID 29334357, 2018). "Prx II is overexpressed and localized to both cytoplasm and nucleus in AR-expressing prostate cancer cells." (PMID 30177619, 2018). "Asperindole A was proved to be highly cytotoxic in 22Rv1 human prostate cancer cells resistant to androgen receptor-targeted therapies." (PMID 29987238, 2018). "The Androgen Receptor (AR) is a key molecule in the development, maintenance and progression of prostate cancer (PC)." (PMID 29423094, 2018). "PCAT3 and PCAT9 have been reported to be predominantly expressed in androgen-dependent prostate cancer cells and appear to be an essential component of androgen receptor (AR) signaling." (PMID 29552304, 2018). "As p62 has been shown to transcriptionally regulated by AR and suppress autophagy in prostate cancer, we found the expression of p62 was reduced when coculturing with endothelial cell, followed by LC3B induction." (PMID 30200999, 2018). "Multiple growth-promoting and survival pathways interact with AR signaling and are involved in prostate cancer." (PMID 29734647, 2018). "High levels of the expression of TRIM36 were observed in the AR-positive prostate cancer cell lines (LNCAP and C4-2), whereas RWPE-1 cells rarely exhibited expression of TRIM36." (PMID 29449534, 2018). "Recent RNA-sequencing-based analysis of the androgen response of prostate cancer cells grownin vitro and within patients following ADT identified a set of 700 genes whose transcription is regulated by the AR in prostate cancer cells." (PMID 30271587, 2018). "Analysis of prostate cancer datasets revealed that the AR RNA fold change in prostate cancer is similar to the present findings in GBM." (PMID 29731997, 2018). "This work facilitates our understanding of the interaction mechanism of DC3 binding to AR at the molecular level and contributes to the rational cyclopeptide drug design for prostate cancer." (PMID 29755968, 2018). "The action of endothelial cells by enhancing the metastatic activity of prostate cancer was via repressing both AR expression and AR transcriptional activity." (PMID 30200999, 2018). "Androgen receptor (AR) signaling is the main driver of prostate cancer (PCa) progression, and stromal cells in the TME also express AR." (PMID 29808619, 2018). "MAGE-A11 was found to play a crucial role in the androgen receptor (AR) signaling network in prostate cancer." (PMID 30185218, 2018). "A close crosstalk exists between IGF1R and androgen receptor (AR), a transcription factor acting as a driver in prostate cancer." (PMID 29462882, 2018). "It has been stated that PRNCR1 is involved in the development of prostate cancer by activating androgen receptor (AR)." (PMID 29802154, 2018).
prostate carcinoma (continued). "Radiotherapy combined with hormone therapy is a standard of care for prostate cancer at many stages, but limited information is available regarding the combination of next generation androgen-receptor signaling targeted drugs and radiohormonotherapy." (PMID 29774129, 2018). "C21 decreased the expression of AR and reduced the proliferation activity effectively in prostate cancer cells and TRAP rat prostate." (PMID 29568400, 2018). "Other studies have shown that Src kinase can promote AR transactivation in C4–2 cells prostate cancer cells." (PMID 31328183, 2018). "NCOA4 was originally identified in a yeast-two hybrid screen as a coactivator of the androgen receptor (AR), enhancing its transcriptional activity in prostate cancer." (PMID 30360520, 2018). "Here we report outcomes of direct and indirect co-cultures of immortalised AR-positive (PShTert-AR) or AR-negative (PShTert) myofibroblasts with prostate cancer cells." (PMID 29721186, 2018). "The ETS genes are fused to the promoters of the androgen receptor target genes, leading to their high expression in prostate cancer cells." (PMID 30291252, 2018). "AR’s role in driving prostate cancer was defined following the observation that androgen starvation by castration can halt disease progression." (PMID 29317749, 2018). "On the other hand, prostate cancer stem cells are characterized by heterogeneity, including AR+ and AR-, which are reflected in their response to hormone treatment." (PMID 29552304, 2018). "In prostate cancer, overexpression of Male Germ Cell-Associated Kinase (MAK), a male-specific kinase and co-activator of androgen receptor leads to increased expression level of GINS2 by mRNA profiling." (PMID 30413605, 2018). "In this study, we showed that MYLIP is a novel E3 ubiquitin ligase that recognizes the AR as its target protein in prostate cancer cells." (PMID 29707137, 2018). "To further study the effect of CCL5 on prostate cancer cells and AR, we treated C4–2 or CWR22Rv1 with CCL5 respectively." (PMID 30200999, 2018). "These show that inhibition of the DNA repair machinery can be used as a strategy to reduce androgen signaling in prostate cancer cells, and support the view that DNA repair makes an important contribution to AR-dependent transcription." (PMID 30305041, 2018). "SiRNAs have been used to target specific AR exons, for example exon 1 in human prostate carcinoma 22Rv1 cells reduced cell proliferation." (PMID 29693622, 2018). "Microarray gene expression analysis reveals that AR activity signature in prostate cancer tissues is decreased after hormone therapy and in CRPC." (PMID 29555975, 2018). "Using specific antibodies against CNPY2 and AR, immunohistochemistry showed that, as with the cell studies, CNPY2 and AR were co-localized in the prostate cancer tissues of patients." (PMID 29707137, 2018). "It has been reported that protein CDK5 can activate and stabilize AR in the nucleus through Ser-81 phosphorylation in prostate cancer cells." (PMID 30367578, 2018). "We have shown that myofibroblasts stably transduced with AR prevented the growth of prostate cancer cells, even though the experiments were performed in stripped media which has no, or a very low, concentration of androgen." (PMID 29721186, 2018). "Hormone or androgen-deprivation therapy (ADT), which acts to suppress the androgen receptor (AR) signaling by androgen depletion or AR antagonists, is still the principal treatment option for locally advanced and metastatic prostate cancers." (PMID 29555975, 2018). "Because prostate cancer cells depend on the androgen receptor (AR) for survival and growth, treatment for recurrent or primary metastatic prostate cancer targets this receptor axis." (PMID 29974203, 2018).
prostate carcinoma (continued). "Our findings increase the number of known AR regulated mRNA isoforms by 10 fold and imply that pre-mRNA processing is an important mechanism through which androgens regulate gene expression in prostate cancer." (PMID 30271587, 2018). "Studies confirm that gain and loss of function of HSP27 are strongly related to the expression of the AR in myogenic cells and prostate cancer cells." (PMID 29699584, 2018). "Our findings show that AR modulates specific progenitor properties of CARNs, including their ability to serve as a cell of origin for prostate cancer." (PMID 29334357, 2018). "AR is a well-established drug target for prostate cancer, which is the second most common cancer by occurrence in men in western countries." (PMID 29867496, 2018). "Our study identifies HDAC3 as a common upstream activator of AKT and AR signaling and reveals that dual inhibition of AKT and AR pathways is achievable by single‐agent targeting of HDAC3 in prostate cancer." (PMID 29523594, 2018). "But, Prx II upregulation and localization mechanisms and the mechanisms by which Prx II affects AR-target genes and Prx isoforms in AR-expressing prostate cancers are yet to be further explored." (PMID 30177619, 2018). "To confirm this, we knocked down AR expression by transfecting prostate cancer cells with siRNA targeting AR." (PMID 30200999, 2018). "The Androgen Receptor (AR) is the key-driving transcription factor in prostate cancer, tightly controlled by epigenetic regulation." (PMID 30464211, 2018). "Integrative clustering, combining RNA-seq data with ChIP-seq for AR and the three histone modifications (H3K4me3, H3K27ac, H3K27me3) revealed three distinct prostate cancer subtypes." (PMID 30464211, 2018). "To address this question, we have studied the effect of AR expression in prostate myofibroblasts on the outcomes of direct and indirect co-culture with prostate cancer cells." (PMID 29721186, 2018). "We next turned to a prostate cancer cell line model for AR-V7 activation through transfection of an AR-WT or AR-V7 expression construct into the LNCaP cell line." (PMID 29760584, 2018). "Guo and colleges showed that knockdown of AR decreased miR-17-92a cluster expression, containing miR-17, -18a, -19a/b, -20a and miR-92 family, in LNCaP cells as well as other AR-positive prostate cancer cell lines." (PMID 30001402, 2018). "For instance, it was shown that in PTEN-deficient prostate cancer cell lines, inhibition of the PI3K pathway increases androgen receptor signalling, while androgen receptor inhibition activates AKT signalling." (PMID 30103709, 2018). "Enzalutamide, a second-generation small-molecule inhibitor of the androgen receptor (AR), has been approved for patients who failed with androgen deprivation therapy and have developed castration-resistant prostate cancer." (PMID 29911070, 2018). "HDAC3 inhibitor shows efficacy in these two prostate cancer subtypes that share activated AR and AKT pathways." (PMID 29572264, 2018). "The PI3K/Akt pathway is important in both androgen-sensitive and hormone-refractory prostate cancer, with functional cross-talk between the pathway and the AR activity involved in both the initiation and progression of prostate cancer." (PMID 29416736, 2018). "Hormone therapy drugs, such as bicalutamide and enzalutamide, directed against prostate cancer focus on androgen receptor (AR) signaling and are initially effective, but the disease progresses to lethality as resistance to these drugs develops." (PMID 29449534, 2018). "Here, the authors show that TRIM28 interacts with TRIM24 to prevent SPOP-mediated ubiquitination of TRIM24 and enhances TRIM24 and AR signaling to induce prostate cancer tumorigenesis." (PMID 30479348, 2018). "Tip60, an oncogene, accelerates cell growth by regulating androgen receptor translocation into the nucleus in prostate cancer." (PMID 29435417, 2018).
prostate carcinoma (continued). "Accumulating evidence suggests that advanced prostate cancer engages androgen-independent signal transduction pathways that inhibit apoptosis, and hence, “bypass” the requirement for AR activation." (PMID 29973512, 2018). "In contrast to prostate cancer, efficient penetration of the AR antagonist through the blood-brain-barrier is obligatory for the treatment of brain tumors." (PMID 29731997, 2018). "Genistein also seems to be effective in the prevention of prostate cancer since it decreased androgen receptor (AR) expression in prostate cancer cells through inhibition of HDAC6-Hsp90 interaction." (PMID 30627525, 2018). "A fourth protein marker, androgen receptor (AR), is a member of the steroid receptor family and is expressed in 60–80% of breast tumors at levels comparable to prostate cancer." (PMID 29382369, 2018). "Together, these studies provide strong evidence that there are ligand independent effects from AR expression in prostate cancer myofibroblasts." (PMID 29721186, 2018). "Since the 1940s, the treatment of advanced prostate cancer has focused almost exclusively on inhibiting the androgen receptor (AR)-signaling program." (PMID 29856824, 2018). "Recent findings suggest that 3β-hydroxysteroid dehydrogenase is induced upon androgen stimulation via androgen receptor in prostate cancer cells, establishing an androgen production positive feedback loop." (PMID 30386380, 2018). "They performed a xenograft tumor growth assay on two different prostate cancer cell lines: LuCaP 86.2, which expresses wild-type androgen receptor (AR) and ARv567, and LuCaP 23.1, which expresses wild-type AR and ARv7." (PMID 29682426, 2018). "The Androgen Receptor (AR) is the main driver of prostate cancer and functions in conjunction with chromatin modifications." (PMID 30464211, 2018). "Our data suggest that dual inhibition of AKT and AR signaling in prostate cancer, especially in those with genetic alterations such as PTEN loss, can be achieved by single administration of HDAC3‐specific inhibitor." (PMID 29523594, 2018). "AR signaling plays a critical role in prostate cancer cell proliferation, survival, and differentiation." (PMID 31328183, 2018). "In particular, HDL reduced ROS levels in AR-positive and AR-null cellular lines of prostate cancer, thus inhibiting ROS-induced cell entry in the G2/M phase." (PMID 29396407, 2018). "Our earlier studies showed an association between ADT, using AR antagonist Casodex, and upregulation of FGD4 in androgen sensitive prostate cancer cells." (PMID 30558664, 2018). "In prostate cancer, AR was confirmed to bind to the PEG10 promoter region, thus repressing the transcription of PEG10." (PMID 30123090, 2018). "AR shows higher expression in the prostate cancer group, with log2 fold change of ~ 1.43 comparing to the benign group." (PMID 30367578, 2018). "The tumor promoting effect of PRDX2 was demonstrated in colorectal carcinoma through up-regulation of Wnt/β-catenin pathway, and prostate cancer through increased activation of the androgen receptor (AR) signaling pathway." (PMID 30104402, 2018). "Cys-C was also found to modulate the invasion of prostate cancer cells by means of the androgen receptor and MAPK/Erk2 pathways." (PMID 29789781, 2018). "Androgen receptor (AR) signaling is crucial for normal prostate development, but also drives the growth and survival of prostate cancer cells." (PMID 30271980, 2018). "The common treatment options for prostate cancer include orchiectomy and hormonal-deprived therapy, both of which function by restricting androgen/androgen receptor (AR) functions." (PMID 30154312, 2018). "Together, our results indicate that MDMX regulates the AR stability in prostate cancer cells by modulating the MDM2 E3 ligase function towards AR." (PMID 29464071, 2018).